RN7SL368P (RNA, 7SL, cytoplasmic 368, pseudogene)
Gene: Miscellaneous RNA gene on chromosome 19 (43,660,500 to 43,660,776, reverse strand). Ensembl gene ENSG00000239948.
Homologues: Orthologues: chimpanzee Metazoa_SRP (99% identical), macaque Metazoa_SRP (92% identical). Paralogues in human: RN7SL1 (83% identical), RN7SL2 (83% identical), RN7SL3 (83% identical), RN7SL769P (83% identical), RN7SL650P (82% identical), RN7SL478P (82% identical), RN7SL341P (81% identical), RN7SL543P (81% identical), RN7SL45P (81% identical), RN7SL480P (81% identical), RN7SL88P (81% identical), RN7SL357P (81% identical), and 704 more.